TGFB1 (transforming growth factor beta 1)
Diseases named in the same sentence as TGFB1 in open-access papers (continued):
Sharing a sentence is not in itself a finding about the gene and the disease.
tumor (continued). "Moreover, we observed that TGFB1 promotes tumor cell migration." (PMID 34131649, 2021). "Interestingly, the expression of DCK was associated with the gene markers like CCR8, STAT5b, and TGFB1 of Tregs, and PD–1, CTLA–4, LAG3, TIM–3, and GZMB of exhausted T cells after adjusting tumor purity, revealing that increased expression of DCK was associated with immunosuppression in HCC." (PMID 32690026, 2020). "Upon activation, we observed altered transcription of KITLG, TGFB1, IFNG, SPP1, IL17A and PDCD1, whose associated functions and expression pattern marked and improved OS of BrC patients, supporting that MCs contribute with a tumor stroma with anti-tumoral functions in BrC." (PMID 32722549, 2020). "Exosomes from PCa cell lines contain TGFβ1, which stimulates the differentiation of fibroblasts to highly aggressive myofibroblasts, an important source of matrix-remodeling proteins within the tumor microenvironment, via the activation of TGFβ/SMAD3 signaling, and thereby support PCa angiogenesis." (PMID 32842503, 2020). "In view of the important role of myofibroblasts in the remodeling of tumor interstitial microenvironment, the blockage of TGFβ1-Smad signaling pathway in MSCs may simultaneously affect the remodeling of tumor interstitial microenvironment and further affect the development of tumor." (PMID 31528217, 2019). "Indeed, according to the “TGFβ1 paradox” concept, this cytokine acts as a potent growth inhibitor in healthy epithelia and during early tumor phases while at later stages it promotes the metastatic process by supporting invasion of cancer cells and metastatic niche formation." (PMID 30805306, 2019). "Other genes were also found to be up-regulated, including Bmp7, which antagonizes transforming growth factor β1 (TGFβ1)-mediated fibrosis through suppressing epithelial-mesenchymal transition, and Mmp8, which prevents metastasis formation through the modulation of tumor cell adhesion and invasion." (PMID 30621584, 2019). "Consequently, pre-treatment and follow up treatment with PRP might decrease TGFβ-1 and, subsequently, it might impair CSCs tumour engrafting, niche formation and even CSCs subpopulation activation." (PMID 31388092, 2019). "We found that the combined DC101 and anti‐TGFβ1 antibody treatment significantly enhanced the intratumoral delivery of the fluorescence nanoparticles, resulting in deeper tissue penetration and a more homogeneous distribution of these particles within the tumor interstitium." (PMID 30886813, 2019). "A significant co-occurrence of an upregulation of the mRNAs of MYO10, MYH9, MYO1E and TGFB1 was observed in the LUSC patients of the TCGA cohort, suggesting that the exposure of tumor cells to elevated levels of TGFβ might have stimulated upregulation of motility and invasion-related myosins." (PMID 29934580, 2018). "Therefore, we also measured TGFβ1 levels in the serum of tumor-bearing TiRP mice." (PMID 29123081, 2017). "Alternatively, high levels of Ki-67 may overwhelm tumor suppressor effects of TGFβ1." (PMID 27895310, 2017). "Furthermore, it has been shown that pirfenidone inhibits proliferation, migration, and epithelial-mesenchymal transition of a human epithelial cell line, disrupted tumor-stromal interactions in pancreatic cancer, and inhibited TGFβ1-induced overexpression of collagen type I in A549 cells." (PMID 26935219, 2016). "Importantly, concerns about aberrant lymphoproliferation of TGFβ1-resistant CTL have been addressed in a non-tumor murine model using human papillomavirus E7-specific CTL, and spontaneous proliferation of dominant negative TGFβRII-engineered CTL did not occur in the absence of antigenic stimulation." (PMID 27589814, 2016). "Similarly, tumor cells may escape growth inhibition by autocrine/paracrine TGFβ1 signaling through alterations to SMAD signaling components." (PMID 27589814, 2016).
tumor (continued). "After the transfection of BX357664, cells were stimulated with recombinant human transforming growth factor-beta 1 (Rh TGF-β1) to upregulate the protein level of TGF-β1 to verify if tumor behavior could be rescued by restoring TGF-β1 expression in the presence of BX357664 overexpression." (PMID 27806310, 2016). "Therefore, the combination of altered TGFβ1 signaling within tumor cells and traditional TGFβ1 signaling within other cell types in the tumor microenvironment results in pleiotropic effects by this cytokine that create a “perfect storm” ideally suited for tumor progression." (PMID 27589814, 2016). "Moreover, the restoration of higher levels of miR-217 prompted mesenchymal to epithelial transition (MET) in TGF-β1 (transforming growth factor beta 1) treated PC cells, unveiling a strong link of this miRNA with late tumor stage, lymphatic invasion, vascular infiltration and distant metastasis." (PMID 27187371, 2016). "Interestingly, the tumour suppressor TGFB1 was among the 361 common DEGs and was identified using IPA as a transcriptional regulator whose known target genes overlapped significantly with the 361 common DEGs (Fisher's exact test P value 0.002, activation z-score −3.4)." (PMID 26245647, 2015). "Additionally, TGFβ1 contributed to the overall tumor-promoting environment through diminished anti-tumor immune activity, and could act as a side-effect via the postulated feedback loop created by the increased level of proliferation in the splenic tissue." (PMID 26253138, 2015). "Therefore, LRG may inhibit implanted LLC tumor growth by additional mechanisms other than enhancing TGFβ1 signaling." (PMID 25826092, 2015). "TGFβ1 is widespread in the human leukocyte antigen system, and it can inhibit the inflammatory response; it can also play an important role in tumorigenesis by promoting tumor metastasis and angiogenesis, as well as changing the microenvironment and evading immune attack." (PMID 25793716, 2015). "This association may coincide with estrogenic response on gene expression and highlight the effect of TAM usage in hyperthyroid patients, especially considering the proliferative and apoptotic effects of TGFA and TGFB1, respectively, on the initial tumor progression stages." (PMID 24701358, 2014). "Thus, TGFβ1 may have a dual role in cancer development, suppressing tumor growth during the initial phases of carcinogenesis but promoting tumor progression and metastasis in more advanced stages." (PMID 23840350, 2013). "However, the TGFβ1 they secrete might create a pro-oncogenic microenvironment more advantageous for tumor growth by affecting stromal cells, such as fibroblasts." (PMID 23755307, 2013). "Treating MSCs with recombinant TGFβ1 and TGFβ3 in the presence of FaDu CM led to significant inhibition of the observed phenotype at the cellular and molecular level, which further implicated TGFβ signaling in negatively regulating MSC differentiation in response to tumor CM." (PMID 24405819, 2013). "Therefore, the fact that Pan02 cells have undergone or are in the process of EMT, suggests that the excess TGFβ1 during tumor progression in SPARC−/− mice might directly stimulate their migration and subsequent metastasis." (PMID 22348081, 2012). "Further, TGFβ1 is an extremely potent immunosuppressive factor that inhibits proliferation, activation and differentiation of immune effector cells, thus its over-expression might contribute to promoting the invasive and metastatic behavior of tumor cells." (PMID 22848630, 2012). "For instance, during the early phase of breast tumorigenesis, theTGFβ signal inhibits primary tumor growthvia cell growth arresting and promoting apoptosis.However, at later stage, cancer cells acquire a capacity to escape from thetumor suppressive effects of TGFβ1 via induction of EMT." (PMID 18615188, 2008).
tumor (continued). "However, TGFβ1 is known to be involved in tumor suppression and its down-regulation following cisplatin treatment could represent a compensatory mechanism to this drug action." (PMID 18302766, 2008). "Therefore, the inhibition of tumor proliferation by PPARγactivators may be explained in part by PPARγ-dependent TGFβ1 repression, supporting the concept that the PPARγ activators may be applied forcontrolling TGFβ1-induced cancer metastasis and fibrosis." (PMID 18615188, 2008). "In conclusion, the result showing that PPARγ activation upregulates PTEN,which has also been implicated in tumor-inhibitory or anti-inflammatory actionsof PPARγ, gives credence tothe concept that PPARγ activators induce PTEN duringS6K1 inhibition, and consequently causes TGFβ1 repression." (PMID 18615188, 2008). "This suggests that secreting higher levels of TGFβ1 may provide an advantage to tumour cells." (PMID 16404434, 2006). "In vitro assays confirmed that endothelial cells were educated by SLC1A3hi tumor cells that undergo malignant transition, drastically upregulating immune-suppressive factors, including CD274, TGFB1, IL10, and IDO1." (PMID 42112375, 2026). "Transforming growth factor beta 1 (TGF-β1) is a multifunctional cytokine involved in organ development, immune response, tumor biology and injury repair." (PMID 41642851, 2026). "These interactions were enriched in growth factor- and cytokine-mediated pathways, including TGFB1-TGFBR2, IL6-IL6R, and EGF-EGFR signaling, suggesting that AP1AR upregulation amplifies paracrine networks supporting tumor proliferation and immune remodeling." (PMID 41438582, 2026). "Originating from resident fibroblasts under the influence of tumor-derived signals, particularly transforming growth factor beta 1 (TGF-β1), CAFs gain a myofibroblast-like phenotype and actively support tumor growth, invasion, and metastasis." (PMID 40710343, 2025). "Monitoring DNA methylation of TGFB1, TGFB2, and TGFB3 provides a robust method for characterizing tumor microenvironments and selecting candidates for immunotherapy in cold tumors." (PMID 40565031, 2025). "CDKN2A and CDC20 expressions correlated significantly with stage and grade, while TGFB1, CDKN2A, and CDC20 were highly expressed in proliferative tumor cells." (PMID 40256740, 2025). "In colorectal cancer (CRC), interactions between SPP1+ macrophages and FAP+ fibroblasts, mediated by macrophage-derived factors such as TGFB1 and IL1A/B drive the development of a fibrotic barrier along the tumor margin." (PMID 41425545, 2025). "The differentially expressed cytokines between tumor-bearing and tumor-free mice included CSF2, TGFB1, IL33, IL1B, and EGF." (PMID 41214328, 2025). "Prior studies have also shown that IR, especially high-LET radiation induces a robust SASP characterized by increased secretion of TGFβ1, MMP9, IL-6, and IGFBPs, promoting chronic inflammation and tumor progression." (PMID 41516087, 2025). "Therefore, the decrease in metabolic gene expression mediated by anti-miR-27a-3p could be related to TGFB1 downregulation, which weakens the tumor’s immunosuppressive profile and regulates key metabolic characteristics of cancer cells, ultimately leading to apoptosis." (PMID 40943648, 2025). "This 3D model provides a platform to study TGFB1-driven EMT, a key mechanism in tumor growth and metastasis." (PMID 41209344, 2025). "Immune cell infiltration levels, including CD4, CD8, FOXP3, CD163‐positive cells and expression levels of TGFβ1 and SMAD3 proteins in tumor tissue were evaluated by immunohistochemistry." (PMID 41187938, 2025). "Our study revealed a correlation between MMP14 expression and various molecules regulating tumor immune cells, including CSF1R, HAVCR2, KDR, PDCD1LG2, TGFB1, CD70, CD86, and CXCL1." (PMID 40352589, 2025).
tumor (continued). "NicheNet indicated that tumor‐derived chemokines (CCL5, TGFB1) interacted with Tregs receptors (CCR4, CCR5, CXCR3), promoting the Treg recruitment." (PMID 41028931, 2025). "Secretion levels of fibroblast growth factors, including EGFR, VEGF, TGFB1, and PDGF-BB, were decreased in the medium of CNPY3-knockdown cells, indicating a potential paracrine effect of CNPY3 on the tumor stroma." (PMID 40055606, 2025). "It reveals reciprocal TGFβ1‒PLVAP crosstalk between tip cells and tumours, proposing vascular‐targeted strategies to disrupt early metastatic niches." (PMID 41431249, 2025). "Between ARGs_High tumour cells and T cells, ITGB2-ICAM1 and TGFB1-TGFBR1 were ligand-receptor pairs with strong regulatory potential, while EDN1, JUNB, SOCS3, VIM and COL1A2 were top genes target to TGFB1." (PMID 40830065, 2025). "Knockdown of MALAT1 effectively inhibits TGFβ1-induced EMT, highlighting its role as a downstream effector of TGFβ-mediated tumor progression." (PMID 41437175, 2025). "The DEGs included genes involved in cell proliferation and migration (e.g., COL11A1), tumor‐promoting factors that degrade the extracellular matrix (e.g., MMP11), as well as immunosuppressive (TGFB1) and proinflammatory responses (TNFRSF6B, IFNGR2, GSDMB)." (PMID 40952312, 2025). "Conventional T cells are converted to CD4 + CD25highFoxP3+ Treg cells in a way that is reliant on TGFβ1 and IL10 since neutralizing antibodies specific to TGFβ1 and/or IL10 prevents tumor-derived EVs from proliferating Treg cells." (PMID 40407494, 2025). "Cell-cell communication is also of importance in shaping the TME, where metastatic survival depends on specific signaling (through CXCL12-CXCR4) between GPX4+ tumor and NOX4+TGFB1+CXCL12+ CAFs." (PMID 41450739, 2025). "Our observations are therefore in line with the established role of TGFB1 as a potent inducer of EMT in PDAC, its key role in the tumor microenvironment, and its correlation with invasive capabilities and metastasis potential." (PMID 41209344, 2025). "We found that macrophages, which served as the source cells of tumor, showing stronger interaction strength with other cell types, especially fibroblasts and hepatocytes, and the SPP1, PTN, CCL, TGFB1 and PLAU pathways were more enriched in tumor regions." (PMID 40230843, 2025). "We found that TGFB1/EGFR, LTA/LTBR, CD46/JAG1, and AREG/EGFR ligand‐receptor pairs were stronger in CD4+ T cell‐Plac1+ tumor cells than in CD4+ T cell‐Plac1− tumor cells, among which LTA/LTBR expression was highly specific for Tregs and Plac1+ cells." (PMID 40056047, 2025). "Collectively, these findings emphasize the central immunoregulatory function of TGFβ1+ Tregs in CRC progression, highlighting them as potential therapeutic targets for modulating the tumor microenvironment and restoring antitumor immunity." (PMID 40891683, 2025). "miR-184 was shown to inhibit transforming growth factor beta 1 (TGF-β1)-induced EMT, thereby reducing metastatic potential and reinforcing its tumour-suppressive activity." (PMID 41379397, 2025). "This study identifies endothelial PLVAP as a prognostic marker in LUAD, linking tumour‐derived TGFβ1 to PLVAP‐driven vascular remodelling and tumour invasiveness." (PMID 41431249, 2025). "This core network of IL-19, TGFβ-1, CXCR4, BMP1, VCAN, and WNT2 reveals a tight-knit module that regulates tumor aggressiveness, immune evasion, and therapy resistance." (PMID 41348904, 2025). "Across all three tumor grades, we observed upregulation of two factors: TGFB1 (TGF‐β) and FN1 (fibronectin) in α‐SMA+ stroma AOIs when compared to all other tissue type AOIs." (PMID 39245631, 2025). "The TGF-β/SMAD pathway, initiated by TGFB1, activates SMAD3, promoting ECM generation and remodeling, which facilitates tumor metastasis." (PMID 40989695, 2025). "For TGFB1 and the receptors TGFBR1 and TGFBR2, a higher expression was detectable in tumor tissue compared to vestibular nerve tissue, which is congruent with the CSF data." (PMID 39272860, 2024).
tumor (continued). "The network of the most promising miRNA-target interactions showed that several tumor suppressor and oncogenic miRNAs target and regulate critical genes, including MYC, CREB1, TIMP3, CCNE1, and TGFB1, which were shown to be involved in WT pathogenesis." (PMID 39473825, 2024). "TGFB1 is a multifunctional cytokine, that exhibits dual origins in HCC as it can be produced by HCC cells or the surrounding tumor stroma." (PMID 39555097, 2024). "Of note, exogenous TGFβ1 and CM from FHC cells pretreated with mtDNA-rich EVs synergistically promoted tumor progression." (PMID 38688896, 2024). "Cytokines, including CCL2, CCL5, CCL18, TGFB1, and GDF15, are produced by tumor cells and attract immune cells, such as macrophages and lymphocytes, from the blood and bone marrow into the tumor microenvironment." (PMID 39272860, 2024). "Collectively, these findings indicate that the establishment of the self-sustaining TGFB1 and CXCL12 autocrine signaling gives rise to tumor-promoting CAFs (myCAFs)." (PMID 39335478, 2024). "In contrast, during angiogenesis, the tip cell secretes Transforming Growth Factor Beta 1 (TGF-β1) and periostin, allowing reactivation of the dormant tumor cells, their proliferation, and metastatic development." (PMID 39682261, 2024). "In a large genetic study, TGFB1 expression in CML was positively correlated with levels of NK and T, which revealed a tumor-suppressive role." (PMID 38673624, 2024). "In another chemoresistance mechanism, the crosstalk between the tumor cells and CAFs promotes the activation and expression of FOXO1, which leads to TGFβ1 expression through autocrine/paracrine loops in ESCC." (PMID 39075612, 2024). "Further database analysis (TIMER2.0) showed that PDCD1 gene expression was positively correlated with the levels of immunosuppressive genes (CD274, PDCD1LG2, TGFB1, and IL10) in most human tumor types." (PMID 38441961, 2024). "The functional assessment of MDSCs through the analysis of PTGS2, S100A8, IL10, TGFB1, and VEGFA expression provides a comprehensive view of their immunomodulatory activities within the tumor microenvironment." (PMID 39916959, 2024). "Among these, IL-1B, IL-6, TNF, CXCLs, TGFB1, HMGB1, STAT3, and STAT5 have been reported to contribute to tumor formation." (PMID 39156107, 2024). "ASCs are a source of several molecules that are thought to promote tumor development such as IGF-1, transforming growth factor beta 1 (TGFβ1), vascular endothelial growth factor (VEGF), hepatocyte growth factor (HGF), and IL-8." (PMID 38159164, 2024). "TGFβ1/Smad, Wnt/β-catenin and MAPK pathways that promote tumour cell apoptosis, inhibit angiogenesis and attenuate inflammatory responses to achieve anti-cancer effects." (PMID 38698812, 2024). "To demonstrate the role of ERS-related genes in PDAC cells, we first analyzed the expression level in tumor and normal tissues of HMOX1 and TGFB1 using the TCGA, GSE41368 and GSE62165 datasets." (PMID 37653101, 2023). "Blocking ATX activity changed the phenotype of the mice by decreasing the plasma concentrations of CXCL9, CXCL10, and CCl2 and the tumor concentrations of LIF, TGFβ1, TGFβ2, and prolactin." (PMID 37296899, 2023). "Mouse mammary EpXT tumor cells, on the other hand, is continuously in EMT through cooperative effects of TGFβ1 and oncogenic Ras signaling." (PMID 38055067, 2023). "In this space, cytokines and chemokines such as TGFβ1, IL-6, IL-6Rα and IL-8 (CXCL8) drive the tumor toward an aggressive mesenchymal state, while IL-10, IL-1RA and TGFβ1 actively suppress expression of immune effector functions." (PMID 37063842, 2023). "The gene and protein expressions of VEGFA, E-cadherin, TGFβ1, EGFR, and bFGF in tumor cells were assayed at the 3 different doses of the anti-PD-L1 antibody." (PMID 38152616, 2023). "Transfection of NK cells with the tumor suppressor miR-186 led to the downregulation of TGFBR1 and TGFBR2, thereby preventing TGFβ1-dependent inhibition of NK cell cytotoxicity." (PMID 38248313, 2023).